SMIM43 (small integral membrane protein 43)
Description:
Required for mesendoderm differentiation (By similarity). Interacts with glucose transporters and promotes glucose uptake. Probably augments the glucose uptake capacity of glucose transporter proteins to meet the energy needs of mesendoderm differentiation (By similarity).
Synonyms: NEMEP; TMEM155
Tractability: Antibody: UniProt places it where antibodies can reach, with medium confidence; UniProt predicts a signal peptide or a membrane-spanning region; its Gene Ontology location is reachable by antibodies, with medium confidence.
Gene: Protein-coding gene on chromosome 4 (121,758,881 to 121,765,427, reverse strand). Ensembl gene ENSG00000164112.
Subcellular location: Cell membrane
Gene Ontology:
Molecular function: transmembrane transporter binding
Biological process: mesendoderm development; positive regulation of D-glucose transmembrane transport
Cellular component: plasma membrane
Homologues: Orthologues: dog SMIM43 (97% identical), pig SMIM43 (95% identical), rabbit SMIM43 (95% identical), mouse Smim43 (92% identical), rat Smim43 (92% identical), tropical clawed frog SMIM43 (37% identical).